FBP1 (fructose-bisphosphatase 1)
Diseases named in the same sentence as FBP1 in open-access papers (continued):
Sharing a sentence is not in itself a finding about the gene and the disease.
tumor (177 papers, 2008 to 2026). "Abundant clinical and experimental evidence suggests that low levels of intracellular FBP1 are associated with drug resistance in tumor cells." (PMID 40100307, 2025). "The low PKLR level of EV, originating from FBP1-deficient hepatocytes, mainly promotes hepatic tumorigenesis by targeting NK cells, reducing the tumor immune response." (PMID 40100307, 2025). "The regulatory role of glycolysis-related proteins, such as fructose-1,6-bisphosphatase (FBP1), which encodes a rate-limiting gluconeogenic enzyme, has been reported to play a role in tumor suppression in many cancers." (PMID 40630951, 2025). "It is also likely that reduced FBP1 and therefore increased glycolysis increases the risk of tumor progression in certain cancer types." (PMID 37388727, 2023). "Consistent with the finding that FBP1 is often downregulated in human cancers, we provide evidence that loss of FBP1 contributes to tumor growth through the Warburg effect in PTEN-deficient PCa." (PMID 36237339, 2022). "This is in line with the fact that FBP1 is also associated with a better prognosis in other tumor entities supporting the relevance of this cross-entity biological effect." (PMID 35477823, 2022). "In colorectal cancer, inhibition of FBP1 by upregulation of its upstream target FOXC1 results in increased tumor proliferation caused by metabolic reprogramming of the malignant cells." (PMID 35477823, 2022). "Fructose-1,6-biphosphatase (FBP1) is a key enzyme in gluconeogenesis and is associated with tumor initiation in several cancers." (PMID 35477823, 2022). "FBP1 is the rate-limiting enzyme for gluconeogenesis and inhibits glycolysis, and inhibition of FBP1 restored the function of tumor-associated NK cells." (PMID 33670082, 2021). "To further elucidate the molecular mechanism underlying the anti-tumor effect of FBP1, we performed mass spectrum analysis in A2780 cells with high expression of FBP1." (PMID 34363022, 2021). "It has been reported that FBP1 possesses a tumor suppressor function and it is often downregulated in many cancers, with the loss of FBP1 linked to tumor progression and poor prognosis in various cancer patients." (PMID 34858835, 2021). "The Ugtla2 gene regulates glycogen/glucose level and promotes the storage of glycogen, and the Fbp1 gene encodes fructose-1,6-bisphosphatase 1, which inhibits glycolysis and tumor growth." (PMID 33968022, 2021). "The reduced transcription of fructose bisphosphates 1 (FBP1), a rate-limiting enzyme in gluconeogenesis, mediates disruptions to gluconeogenesis and increased glycolytic activity, causing tumor progression and poor prognosis." (PMID 35004688, 2021). "Analysis of the correlation of the FBP1 levels (grouped as high or low) with clinicopathological data showed that low-FBP1 expression was negatively associated with ascites, residual tumor size, the chemotherapeutic response, and recurrence." (PMID 34363022, 2021). "Loss of FBP1 is associated with tumor progression and patient prognosis in various cancer types examined 28-30." (PMID 31938049, 2020). "Secondly, their transcriptome analysis of tumor-associated NK cells showed a strong upregulation of fructose- 1,6- bisphosphatase (FBP1) expression, a rate-limiting enzyme in gluconeogenesis." (PMID 33260925, 2020). "In contrast, tumor with lower stage had higher FBP1 expression level, which was negatively associated with tumor stage." (PMID 28394358, 2017). "Most importantly, we demonstrate that low expression of FBP1 associated with the tumor size and the TNM stage of HCC." (PMID 28262837, 2017). "Decreased expression of Fbp1 has recently been associated with tumor growth control consistent with the results obtained in our study." (PMID 23342276, 2012). "Associations between FBP1 and -3 and tumor grade in non-invasive bladder cancer RCC (low, high expression: for definition see text)." (PMID 19087307, 2008).
tumor (continued). "Similarly, FBP1, a gluconeogenesis-related enzyme, has been associated with tumor suppression in various cancers." (PMID 39931063, 2025). "Furthermore, the results of WB from U251 cells showed that changes in proteins related to tumor biological behaviors caused by single GBE1 knockdown were also reversed after FBP1 knockdown, which was paralleled to the alterations in tumor phenotypes." (PMID 36900384, 2023). "Our results also suggest that the deregulation of FBP1 may be the key mechanism of tumor progression driven by Warburg effect in PTEN-deficient PCa." (PMID 36237339, 2022). "Its down-regulation mechanism may be related to DNA hypermethylation of gene promoter or loss of the copy number of the gene, histone deacetylation caused by deregulation of HDACs or degradation of FBP1 in tumor cells caused by the E3 ligase TRIM28." (PMID 36237339, 2022). "FBP1 is often downregulated in many tumor types, and its loss is correlated to tumor progression." (PMID 34830179, 2021). "Our study also showed that FBP1 expression was associated with tumor size, tumor grade, and SUVmax; thus, tumor size, tumor grade, and SUVmax may be good predictors for FBP1 in ccRCC." (PMID 30723389, 2019). "We selected fructose‐1,6‐bisphosphatase 1, FBP1, encoding the gluconeogenesis regulatory enzyme, acting as a rate‐limiting enzyme in gluconeogenesis and a well‐known tumor suppressor in HCC, and fibroblast growth factor 1, FGF1, encoding a well‐known pro‐oncogenic growth factor in HCC." (PMID 29117471, 2018). "Importantly, increased expression of TRIM28 associated with decreased expression of FBP1 and tumor node metastasis stage of HCC." (PMID 28394358, 2017). "Additionally, a highly significant association between high levels of FBP1 and high tumor cell proliferation rate (Ki-67) (p = 0.001) was noted." (PMID 19087307, 2008). "Collectively, FBP1 loss may be involved in the tumor immune escape." (PMID 36230984, 2022). "However, the underlying molecular mechanism responsible for FBP1 functions as a tumor suppressor remains unknown." (PMID 22039417, 2011). "The oncogenic components, namely, ALDH1B1, ALDH1L2, CHSY1, CSGALNACT2, and GPX8, were progressively upregulated in more aggressive tumors, while the tumor suppressor hubs FBP1 and HPGD were downregulated as tumor aggressiveness increased." (PMID 40626022, 2025). "Studies on the dual roles of FBP1 in tumor progression have shown that its expression can influence tumor behavior." (PMID 39902328, 2025). "Previous research confirmed FBP1 as a potential prognostic biomarker correlated with immunosuppressive tumor microenvironment (TME) in GBM." (PMID 39902328, 2025). "Due to its complex biological functions, FBP1 has emerged as a key target in tumor studies in the past few decades." (PMID 40100307, 2025). "Specifically, manipulating FBP1 expression can either promote or suppress tumor progression by enhancing or inhibiting glycolysis and cell growth." (PMID 39902328, 2025). "Although FBP1 mainly functions as an anti-oncogene, it can also act as an oncogene to promote tumor progression." (PMID 40100307, 2025). "Although these chemical inhibitors have been shown to restore FBP1 expression in tumors, thereby inhibiting tumor progression, and some of them have been used clinically." (PMID 40100307, 2025). "In particular, a previous study demonstrated that inhibition of FBP1 in PDAC leads to tumor progression by altering glucose metabolism." (PMID 40630951, 2025). "FBP1, an enzyme that limits the process of gluconeogenesis, hampers the Warburg effect, thus inhibiting tumor development." (PMID 40100307, 2025). "Because of its multifaceted functions, the mechanisms by which FBP1 is involved in tumor development are complex." (PMID 40100307, 2025). "Reduced FBP1 expression was reported to promote tumor growth and resistance to immune checkpoint blockade therapy in mice." (PMID 40100307, 2025).
tumor (continued). "Among the 7 HRGs included in the hypoxia risk score model constructed in this study, these 6 genes (LDHA, PGK1, PFKP, DCN, LOX, FBP1) have been extensively reported in previous studies for their roles in tumor hypoxia response and progression." (PMID 40464853, 2025). "FBP1 (fructose 1, 6‐bisphosphatase 1), a rate‐limiting enzyme in gluconeogenesis, was reported to be downregulated in various tumours, including OS." (PMID 40801794, 2025). "This leads to the upregulation of FBP1, a recognized tumor suppressor, further enhancing its tumor-suppressive impact in CRC." (PMID 39333489, 2024). "In turn, Fbp1–NfκB p65 interaction induces proteasomal degradation of this subunit and inhibits tumor growth." (PMID 39251668, 2024). "This indicates that MT1JP exerts its tumor-suppressing effects in ICC by regulating the miR-18a-5p/FBP1 axis." (PMID 39458127, 2024). "In the FBP1 knockdown group, the levels of the anti‐apoptotic protein bcl‐2 markedly decreased while that of bax increased in A549 and NCI‐H1975 cells, demonstrating that FBP1 plays a tumour‐suppressive role in LC." (PMID 38693853, 2024). "The results revealed a noteworthy decline (P = 1.80 × 10–5) in tumor formation when H1299 cells overexpressed FBP1 (WT) in comparison to the control group." (PMID 38349431, 2024). "The primary objective of this study was to examine the underlying mechanism through which Fructose-1,6-bisphosphatase 1 (FBP1), a gluconeogenic enzyme, functions as a tumor suppressor to regulate the stemness of NSCLC." (PMID 38349431, 2024). "We found that FBP1 was highly expressed in most tumours except LUAD, while FBP1 was also highly expressed in macrophages, which can be used as a marker gene for macrophages." (PMID 38693853, 2024). "Following this, we conducted an examination to ascertain the impact of FBP1 overexpression on the in vitro ability of tumor spheres formation." (PMID 38349431, 2024). "In contrast to mice that were subcutaneously injected with 104 cells individually, the overexpression of FBP1 led to a reduction in tumor weight and growth rate, whereas the overexpression of NICD1 promoted tumor weight and growth rate (P < 0.05)." (PMID 38349431, 2024). "FBP1 is known to have reduced expression in various tumor tissues, including the esophagus, liver, lung, and ovarian cancer." (PMID 38557130, 2024). "The knockdown of FBP1 led to a significant increase in the formation of tumor spheres in PC9 cells, while the simultaneous knockdown of Notch1 reversed this trend." (PMID 38349431, 2024). "Further investigation has shown that FBP1 acts as a metabolic tumor suppressor by inhibiting proliferation, migration, and invasion, resulting in a decrease in aerobic glycolysis and sensitizing cancer cells to chemotherapy‐induced apoptosis." (PMID 36525508, 2023). "Analyses of human HCC specimens revealed lower levels of PERK-mediated FBP1 S170 phosphorylation and nuclear accumulation in the tumor specimens than in their adjacent normal tissues." (PMID 36857532, 2023). "The tumor’s fructose 1,6-bisphosphatase 1 (FBP1), a gluconeogenesis regulatory enzyme, has been demonstrated to inhibit aerobic glycolysis in tumor cells." (PMID 37296673, 2023). "For instance, the results of FBP1 match well with its well-known inhibitory effects on glycolysis and tumor growth." (PMID 38017382, 2023). "FBP1 is a rate-limiting enzyme for gluconeogenesis processes, which can regulate gluconeogenesis processes and is present in most cells, and it plays a tumor suppressor role in many cancer." (PMID 38049890, 2023). "FBP1, a recognized tumor suppressor, is known to inhibit cancer development via inhibition of aerobic glycolysis and suppression of the Warburg effect in different cancer types." (PMID 36237339, 2022). "Glycolysis is an indispensable mechanism for tumor cells to survive; thus, gluconeogenesis function of FBP1 consequently threatens tumor cell survival." (PMID 36430241, 2022).
tumor (continued). "Knockdown of the FBP1 gene led to a significant enhancement of the PD-L1 protein, mRNA expression, and tumor growth." (PMID 36230984, 2022). "Our results reveal a novel tumor-suppressive feature of PTEN in restraining FBP1 degradation and the Warburg effect." (PMID 36237339, 2022). "Fructose-1, 6-bisphosphatase 1 (FBP1), a rate-limiting enzyme for gluconeogenesis, plays a critical role in tumor initiation and progression of ccRCC." (PMID 36176391, 2022). "Identical results demonstrated that an opposite trend between ALDOA and FBP1 was observed between normal and tumor groups." (PMID 35404841, 2022). "Increasing evidence shows that FBP1 is a key enzyme in regulating tumor glucose metabolism, and the deletion of FBP1 gene is related to cancer progression." (PMID 36237339, 2022). "The gluconeogenic rate-limiting enzyme FBP1, which resided on chromosome 9q22, was found to inhibit tumor growth in several cancer types, among others also in KIRC." (PMID 35250999, 2022). "Fructose-1,6-bisphosphatase (FBP1) is a tumor suppressor and a key enzyme negatively regulating Warburg effect in cancer." (PMID 36237339, 2022). "Conversely, expression of the gluconeogenic gene FBP1, a recognized tumour suppressor gene also in CCA, was downregulated." (PMID 35619118, 2022). "Since FBP1 can be activated by miR-24-1 expression induced by enhancer elements, we further studied the function of the FBP1/miR-24-1/enhancer axis in tumor growth via xenograft experiments in vivo." (PMID 35978816, 2022). "As a rate-limiting enzyme in gluconeogenesis, fructose-1,6-bisphosphatase (FBP1) controls the rate of the reaction and works as an important tumor suppressor in human malignancies." (PMID 36358906, 2022). "The role of FBP1 in various cancer entities is undergoing scrutiny in the last decade and it is found to be up-regulated in different tumor types." (PMID 35477823, 2022). "Due to the glucose metabolism‐related effect of FBP1, FBP1 functions as a tumor‐suppressing protein via agonist glycolysis in cancer cells." (PMID 34854226, 2022). "In the TCGA dataset, patients with RCC with lower FBP1 expression exhibited worse survival outcomes, suggesting that FBP1 indeed exhibits a tumor-suppressive effect." (PMID 35978816, 2022). "Defect in FBP1 is associated with poor prognosis of cancer, enhancing EMT function, growth and drug resistance of tumor cells." (PMID 36077431, 2022). "Gluconeogenic enzyme fructose 1,6-bisphosphatase 1 (FBP1) as a metabolic tumor suppressor in HCC, can trigger HSCs activation and senescence by releasing HMGB1 after being deleted in hepatocytes, showing a SASP." (PMID 35971182, 2022). "In the normal and tumor groups, patients with low FBP1 expression had high ALDOA expression (p<0.0001)." (PMID 35404841, 2022). "In this study, we have revealed that PTEN plays a key function in regulating FBP1 expression and tumor progression through FBP1 phosphorylation-dependent ubiquitin degradation in PCa, thus defining a new role of PTEN in metabolism and tumor progression." (PMID 36237339, 2022). "It was reported that FBP1 antagonized glycolysis and thus inhibited tumor proliferation in many types of tumors." (PMID 36057625, 2022). "In esophageal cancer, only little is known about the function of FBP1 and its impact on tumor characteristics." (PMID 35477823, 2022). "Mechanistically, circ-FNDC3B-218aa inhibits the expression of Snail and subsequently promotes the tumor-repressive effect of FBP1, which results in the suppression of tumor progression and EMT." (PMID 35223470, 2022). "82.5% of them showed FBP1 expression in the tumor albeit with different intensities (score 1 = 25.0%, score 2 = 35.9%, score 3 = 21.5%)." (PMID 35477823, 2022).
tumor (continued). "The expression of FBP1 is low in most normal cells but is significantly increased in a variety of tumor cells, including liver cancer cells, oligodendroglioma, non-small cell lung cancer, breast cancer and clear cell renal cancer." (PMID 36000567, 2022). "Downregulating FBP1 expression can promote tumor cell epithelial-mesenchymal transition, proliferation, and resistance to therapeutic efficacy." (PMID 35404841, 2022). "In summary, we have discovered a new role of PTEN in antagonizing Warburg effect by regulating expression of FBP1 and its effect on cell metabolism and tumor growth." (PMID 36237339, 2022). "Collectively, these results indicate that FBP1 can be activated by miR-24-1 and inhibit tumor growth in a manner dependent on enhancer integrity." (PMID 35978816, 2022). "All these studies suggest that epigenetic regulation of FBP1 plays a critical role in modulating tumor initiation and progression in various cancer types." (PMID 34363022, 2021). "The glucose restriction in TME impairs NK cell function by upregulation of fructose-1,6-bisphosphatase (FBP1), an enzyme that inhibits glycolysis, in tumor infiltrating NK cells." (PMID 34858978, 2021). "LIX1-like protein (LIX1L) promotes miR-21–3p, inhibits FBP1, reduces lactic acid production, and affects sugar metabolism to inhibit tumor growth." (PMID 35004688, 2021). "Fluorescence imaging showed that the FBP1 overexpression led to reduced tumor volume and weight following cisplatin treatment, relative to cells harboring empty vector." (PMID 34363022, 2021). "In cancers of various organs (breast, liver, kidney, etc.), FBP1 is a putative tumor suppressor, negatively regulating aerobic glycolysis, reducing the Warburg effect and/or antagonizing the function of HIF." (PMID 34830179, 2021). "Fructose-1,6-bisphosphatase (FBP1) is a rate-limiting enzyme in gluconeogenesis and an important tumor suppressor in human malignancies." (PMID 34363022, 2021). "FBP1 is important in glucose metabolism and inhibits glycolysis in human tumor cells and hematopoietic progenitor cells." (PMID 34177887, 2021). "Of note, FBP1 was reported to be a tumor suppressor constantly deleted in ccRCC that inhibited glycolysis and PPP with direct inhibition of HIF-1α activity, putting FBP1 in the opposite position to PFKFB4." (PMID 34593007, 2021). "Fructose-1,6-bisphosphatase 1 (FBP1) exerted a tumor-suppressive role in HCC by inhibiting the rate of glycolysis and the glycolytic capacity of HepG2 and SK-Hep1 cells." (PMID 34440674, 2021). "FBP1 is a downstream glycoisoenzyme and tumor suppressor that inhibits glycolysis and tumor growth and partially inhibits tumor growth by inhibiting mitotic signal transduction." (PMID 33564363, 2021). "FBP1 protein expression levels were high in a larger percentage of normal tissues (19/23, 82.6%) than tumor tissues." (PMID 34363022, 2021). "further demonstrated that decreased FBP1 expression promotes tumor growth and resistance to ICIs in tumor-burdened mice with STAT3-PD-L1 over-expression, which provides a possible perspective for breaking therapeutic resistance to ICIs." (PMID 34858835, 2021). "We then analyzed FBP1 protein expression in 375 tumor tissues and 23 normal ovarian tissues (FUSCC cohort) by immunohistochemical staining." (PMID 34363022, 2021). "In a KRAS-driven mouse model of lung cancer, aberrantly elevated fructose-1,6-bisphosphatase (FBP1) expression in NK cells from the tumor microenvironment impaired their function by inhibiting glycolysis and reducing their proliferation and viability." (PMID 33670082, 2021). "Next, using murine intraperitoneal xenotransplantation models, we found that overexpression of FBP1 inhibited tumor metastasis, reducing both the number and the weight of peritoneal disseminated lesions." (PMID 34363022, 2021).